MMP7 (matrix metallopeptidase 7)
Diseases named in the same sentence as MMP7 in open-access papers (continued):
Sharing a sentence is not in itself a finding about the gene and the disease.
liver fibrosis (continued). "Moreover, the exact role of VEGF-A and angiogenesis in BA should be further explored, especially in relation to progression of liver fibrosis, cholangiocyte proliferation and potentially MMP-7 as well." (PMID 33409288, 2020). "The role of MMP-7 and other MMPs in liver fibrosis is just starting to be elucidated." (PMID 33409288, 2020). "MMP-7 has been investigated in BA and BA-related liver fibrosis." (PMID 33409288, 2020). "However, as MMP-7 is suspected to be involved in BA, its exact role and significance in the progression of BA-related liver fibrosis requires further investigation." (PMID 33409288, 2020). "Moreover, MMP-7 expression correlates to the extent of liver fibrosis in BA patients at time of diagnosis." (PMID 33409288, 2020). "Moreover, simultaneous observation of serum and stool MMP-7 level could monitor the degree of inflammation, obstruction of the extrahepatic bile duct, and liver fibrosis more objectively than stool color." (PMID 35717157, 2022). "Moreover, good evidence was shown in investigations of serum IL-18 and IL-33 in distinguishing BA from healthy controls, serum IL-18 for prognosis of post-KPE persistent jaundice, and serum hyaluronic acid and MMP-7 for prognosis of post-KPE significant liver fibrosis." (PMID 34083585, 2021). "However, as liver fibrosis is an abnormal process of tissue regeneration, MMP-7 might merely be a (specific) marker of this abnormal regeneration and not play an active role in the pathogenesis of BA." (PMID 33409288, 2020). "Moreover, Kupffer cell expression of MMP-7 increases as liver fibrosis in BA progresses." (PMID 33409288, 2020). "In conclusion, MMP7 promotes liver fibrosis in BA by driving EMT via the E-cadherin/β-catenin pathway, and targeting MMP7 demonstrates anti-fibrotic effects." (PMID 41828435, 2026). "Generation of C-terminal AAT peptides, such as C37 and C42, depends on specific matrix metalloproteinases (MMPs), which contribute to liver fibrosis; for example, MMP-3 is altered in children with AATD, and MMP-7 is upregulated in pediatric biliary atresia." (PMID 41450890, 2025). "MMP-7 not only promoted fibrosis in ILD, but also promoted fibrosis in other tissues, such as kidney fibrosis, liver fibrosis and myocardial fibrosis." (PMID 40722657, 2025). "Second, we found that MMP-7 levels were highly correlated with GGT levels and the liver fibrosis score." (PMID 38141111, 2024). "Matrix metalloproteinase-7 (MMP-7) plays an important role in remodeling the extracellular matrix (ECM), which is closely related to liver damage and liver fibrosis progression." (PMID 38978022, 2024). "Matrix metalloproteinase-7 (MMP-7) plays an important role in remodeling the extracellular matrix (ECM), which is closely related to liver fibrosis progression." (PMID 38034822, 2023). "Blockade of MMP7 alleviated EMT and liver fibrosis in BA mice." (PMID 41828435, 2026). "Besides, the CDCs with higher levels of serum MMP-7 were more likely to suffer liver damage, convinced by the higher levels of ALT and AST, and a higher rate of liver fibrosis." (PMID 38914992, 2024). "Many predicted targets such as TIMP1, MMP2, COL1A1, MMP7, and COL3A1 have been involved in liver fibrogenesis and could be potential therapeutic targets for liver fibrosis." (PMID 35791909, 2022). "The co-localization of MMP-7 and important mediators of hepatic injury and fibrosis provides circumstantial evidence that MMP-7 is actively involved in the initial cholangiocyte injury in BA as well as in BA-related liver fibrosis." (PMID 33409288, 2020). "In liver fibrosis, the role of MMP-7 has not been described extensively." (PMID 33409288, 2020). "In liver fibrosis, the role of MMP-7 has not been accurately described." (PMID 33409288, 2020).
liver fibrosis (continued). "Second, there were notable similarities in biliary injuries and liver damage between CDC patients in group 2 and BA patients in terms of indistinguishable serum MMP-7, GGT, and DB levels, as well as liver fibrosis stages (unreported data)." (PMID 38914992, 2024). "Despite these correlations of MMP-7 with extent of liver fibrosis, a clear demonstration of the longitudinal effects that MMP-7 has on liver fibrosis in BA is lacking." (PMID 33409288, 2020).
melanoma (22 papers, 2006 to 2025). A malignant, usually aggressive tumor composed of atypical, neoplastic melanocytes. "Expression studies in primary cutaneous and metastatic melanomas also revealed MMP7 association with tumor cell invasion and progression suggesting its prognostic value in predicting the clinical behavior of melanoma." (PMID 23437250, 2013). "qRT-PCR in A375 melanoma cells showed significant overexpression of MMP7, MMP11, and MMP14 compared to normal skin cells, further supporting their relevance in melanoma." (PMID 40604111, 2025). "Metalloproteinase-7 (MMP7) expression was demonstrated in the majority of primary tumors and all metastatic tumors in melanomas and therefore was proposed as a prognostic marker." (PMID 34360915, 2021). "According to our data, the protein levels of β-catenin and its downstream factors cyclin D1, c-Myc, MMP2, and MMP7 were all markedly decreased in melanoma cells after DHC treatment." (PMID 33833997, 2021). "Melanoma cell lysates were analyzed by immunoblotting using antibodies against MMP7 and CXCR4, or against β-tubulin as a loading control." (PMID 31227006, 2019). "The overexpression of miR-126-3p/5p was shown to significantly induce apoptosis, and activate caspase-3 and caspase-7 by directly regulating ADAM9 and MMP7 in melanoma." (PMID 25759982, 2015). "To investigate the actual contribution of ADAM9 and MMP7 modulation to miR-126&126*-dependent outcomes, we tested the effects deriving from separately knocking-down these two genes in A375M and Me665/1 melanoma cells." (PMID 23437250, 2013). "Looking for the effectors of these antineoplastic functions, we identified ADAM9 and MMP7, two metalloproteases playing a pivotal role in melanoma progression, as direct targets of miR-126&126*." (PMID 23437250, 2013). "The more aggressive behaviour of different Bcl-2 overexpressing melanomas was associated to an increase in several metalloproteases (e.g. MMP-2, MMP-7, and MT1-MMP) expression, and to an elevated microvessel density as compared to parental cells." (PMID 22233801, 2012). "We also investigated the correlation of the seven prognostic-associated TBCs between MMP-related genes (MMP2, MMP9, MMP7, MMP14, BSG, EGFR, MMP1, MMP3) and EMT-associated genes (TWIST1, VIM, CDH2, ACTA2, ZEB1), which also indicated a central role of TBCs in melanoma." (PMID 33194704, 2020). "STRING-based analysis showed that MMP7, MMP11, and MMP14 formed dense interaction networks with other ECM-related genes, indicating their regulatory significance in SCC and melanoma progression." (PMID 40604111, 2025). "A deeper look into SKCM datasets via TCGA validation revealed that MMP7, MMP11, and MMP14 also exhibited high expression in primary melanoma tumors." (PMID 40604111, 2025). "Immunohistochemistry from the Human Protein Atlas confirmed moderate to strong protein expression of MMP7, MMP11, and MMP14 in melanoma tissues, consistent with transcriptomic findings." (PMID 40604111, 2025). "The plasma and expression levels of MMP-7 and -9 and ADAM-9 are reduced by AC-EO treatment in B16F10-injected mice and in B16F10 melanoma." (PMID 38791435, 2024). "For example, a study analyzing the expression of MMPs in melanoma found that MMP-1, MMP-2, MMP-3, MMP-7, MMP-9, and MMP-13 showed increased levels in melanoma tissues compared to normal tissues." (PMID 39200315, 2024). "In our study, we observed that partial-EMT-related markers N-cadherin and MMP-7 were upregulated, and E-cadherin was downregulated after RBBP5 knockdown in melanoma cells, which agree with previous research about cadherin switch." (PMID 36866240, 2023). "Clinical studies showed significantly increased expression of MMP2 and MMP7 in melanomas, while patients with strong MMP2 or MMP7 had a bad survival." (PMID 33833997, 2021). "Given the recent emphasis on the role of MMP9 and MMP7 during cancer cell migration, we next investigated the effect of ALOC-EO on the migration of B16F10 melanoma cells grown in vitro." (PMID 34360915, 2021).
melanoma (continued). "The extracellular matrix (ECM)-degrading proteases comprising a disintegrin and metalloprotease-9 (ADAM9), matrix metalloproteinase-7 (MMP7), and MMP9 play a pivotal role during melanoma growth, migration, and adhesion." (PMID 34360915, 2021). "Besides, it may play a tumor suppressor role by directly regulating ADAM9 and MMP7 in melanoma." (PMID 33880366, 2021). "Up to date, only ADAM9, MMP7 and PIK3R2 have been validated as direct miR-126-3p&5p target genes in drug treatment-naïve melanoma cells." (PMID 31227006, 2019). "These microRNAs play a tumour suppressor role in human melanoma through down-modulation of two metalloproteinases, ADAM9 and MMP7, resulting in decreased HB-EGF activation." (PMID 24990570, 2014). "Among a number of options, we focused on ADAM9, MMP7 and osteopontin (OPN) for their important role in melanoma progression." (PMID 23437250, 2013). "MMP7 and MMP11, primarily overexpressed in early-stage melanoma, may influence the immunogenic landscape by regulating cytokine processing and enabling immune evasion." (PMID 40604111, 2025). "Our findings suggest that MMP7 and MMP11 may serve as early-stage targets, whereas MMP14 could inform treatment strategies in advanced melanoma and SCC." (PMID 40604111, 2025). "Furthermore, co-treatment with AC-EO and siRNA-EGFR or cetuximab leads to a more effective downregulation of cell proliferation and the expression level of MMP-7 and -9 than individual treatment in B16F10 melanoma." (PMID 38791435, 2024). "MMP7 was found to be down regulated 5-fold by CtBP1 in melanoma, whereas c-myc and laminin gamma 2 were not affected." (PMID 19216735, 2009). "In addition, as ADAM9 and MMP7 share a role in the proteolytic cleavage of the HB-EGF precursor, we looked for the effectiveness of this regulatory pathway in melanoma, confirming the decrease of HB-EGF activation as a consequence of miR-126&126*-dependent downmodulation of ADAM9 and MMP7." (PMID 23437250, 2013). "In melanoma cells the low or absent levels of miR-126&126*, unblocking ADAM9 and MMP7, should result in an increased activation of pro-HB-EGF, consequently producing a higher quantity of HB-EGF-C translocation into the nucleus." (PMID 23437250, 2013). "Moreover, treatment of primary or metastatic melanoma cells with anti-miR-126 and/or 126* LNA oligonucleotides for 48 hours showed a significant increase in the levels of ADAM9 and MMP7 compared with negative control-treated cells as judged by western blot analysis." (PMID 23437250, 2013).
lymph node metastasis (21 papers, 2007 to 2024). "PTP1B promotes invasion and metastasis by regulating the PTEN-AKT/pAKT pathway and promoting the expression of metalloproteinase 2 (MMP2) and MMP7, which is associated with lymph node metastasis." (PMID 34638706, 2021). "CD44, MMP7 and β-catenin expression was positively associated with distant metastasis, lymph node metastasis and tumor-node-metastasis (TNM) stage." (PMID 26408312, 2015). "With the proteolytic activity, MMP-7 expression has been associated with the potential of cancer cell invasion and lymph node metastasis." (PMID 26699938, 2015). "Levels of MMP-7 positively correlate with GC invasion, lymph node metastasis, peritoneal dissemination, and patient survival 33-35." (PMID 38911387, 2024). "Several studies have demonstrated that a high level of MMP-7 is connected to tumorigenesis and lymph node metastasis of tongue cancer." (PMID 34078895, 2021). "In BC, we previously found elevated MMP-7 mRNA, serum and urine levels to correlate with the presence of lymph node metastasis." (PMID 33396213, 2020). "MMP-7 expression increased with lymph node metastasis, and patients with tumours positive for MMP-7 often had neural invasion." (PMID 33005257, 2020). "Lymph node metastases were histopatologically proven in five cases, and all of these cases showed overexpression of MMP-7." (PMID 32751899, 2020). "The higher MMP-7 protein level was observed among 53% of primary cancers and MMP-7 tissue status had a statistically relevant correlation with lymph node metastasis, weak differentiation, and peritoneal dissemination." (PMID 29867026, 2018). "Accordingly, in our included survival studies, we found that high MMP7 level is correlated with invasion depth, lymph node metastasis, distant metastasis and TNM staging." (PMID 25919283, 2014). "Analysis of the relationship between MMP-7 mRNA expression and histopathological parameters demonstrated a significant correlation with depth of infiltration and lymph node metastasis." (PMID 22159423, 2012). "Furthermore, there was a notable rise in the expression of MMP7 in NSCLC patients who had lymph node metastases, in comparison to healthy tissues." (PMID 39187937, 2024). "Importantly, MMP7 expression is most pronounced at the invasive front of tumors, has been reported as an independent prognostic factor which closely correlates with clinical stage, tumor size, lymph node metastasis, and poor survival of oral cancer patients." (PMID 25424420, 2014). "We found markedly elevated expression of MMP7 in human TSCC specimens compared with their respective paired nontumour tissues, and this high expression was correlated with the patients’ lymph node metastasis." (PMID 31937294, 2020). "The expression of CD44, MMP7 and β-catenin showed a positive correlation with TNM stage, distant metastasis and lymph node metastasis (P < 0.05)." (PMID 26408312, 2015).
COVID-19 (20 papers, 2021 to 2025). A disease caused by infection with severe acute respiratory syndrome coronavirus 2. "MMP-2, MMP-7, MMP-8, and neuropilin-1 were positively correlated, aligning with prior findings of elevated MMPs in severe COVID-19, linked to tissue damage and repair." (PMID 40557167, 2025). "In COVID-19, increased MMP7 and MMP9 activity is thought to contribute to lung damage and inflammation through degrading components of the extracellular matrix in the lungs, leading to tissue injury and impaired lung function." (PMID 38803919, 2024). "MMP7 and MMP9 are two enzymes that have been implicated in the context of COVID-19 by interacting with important molecules such as FasL, the respiratory illness caused by the SARS-CoV-2 virus." (PMID 38803919, 2024). "Serum samples were obtained to measure MMP-7 from 42 COVID-19 patients under invasive mechanical ventilation (IMV) in our institute (April–July 2020, derivation cohort)." (PMID 39624381, 2024). "A previous report showed that patients with severe COVID-19 have higher plasma levels of MMP-7 after short-term follow-up (median 9 weeks), displaying an inverse correlation with forced vital capacity (FVC) and diffusing capacity for carbon monoxide (DLCO)." (PMID 39624381, 2024). "The findings of our study not only enhance our understanding of the molecular mechanisms of MMP/FasL COVID-19, but also pave the way for potential therapeutic interventions targeting the MMP7/MMP9 and FasL pathways." (PMID 38803919, 2024). "Four conditions were studied; MMP7/FasL (healthy), MMP7/FasL (COVID-19), MMP9-FasL (healthy), and MMP9/FasL (COVID-19)." (PMID 38803919, 2024). "MMP7 (Healthy, COVID-19) and MMP9 (Healthy, COVID-19) converged to the target of minimization in 644 steps Potential (Energy = −7.6310362e+05), 1014 steps (Energy = −7.7362425e+05); 1910 steps." (PMID 38803919, 2024). "On the other hand, MMP-7 can serve as an indicator of the seriousness of post-COVID-19 lung injuries." (PMID 37372128, 2023). "MMP-7 cytokine levels were correlated with cytokine storm severity and high 4-C scores in the COVID-19 patients." (PMID 36286038, 2022). "The results show that MMP-7 is significantly correlated with the cytokine storm and with a high 4-C score in the COVID-19 patient group." (PMID 36286038, 2022). "High serum levels of MMP7 and MMP9 and the levels of macrophages activation factors, and severity of COVID-19 in obese-diabetic patients were associated with ARDS in COVID-19 patients with risk factors." (PMID 35893698, 2022). "MMP-7 was significantly correlated with a cytokine storm and a high 4-C (severity) score in COVID-19 patients." (PMID 36286038, 2022). "From a host genetic perspective, elevated levels of IL-6, IL-10, IL-13, MMP-7, ferritin, and D-dimer were observed in COVID-19 patients across all genotypes, with the CC genotype associated with the highest concentrations, suggesting a heightened inflammatory and pro-thrombotic state." (PMID 40733568, 2025). "Coul-SR energies were generally lower in COVID-19 vs. healthy groups for both MMP7 and MMP9." (PMID 38803919, 2024). "MMP-7 is a major marker that can detect COVID-19 cases requiring invasive mechanical ventilation." (PMID 38803919, 2024). "Beyond MMP7/9 we recommend research on more MMP molecules that are involved in COVID-19." (PMID 38803919, 2024). "The COVID-19 MMP9-FasL group had more H-bonds compared to MMP7-FasL group (12 vs. 7)." (PMID 38803919, 2024). "MMP7 may serve as an indicator of the continued presence of lung abnormalities after recovering from COVID-19." (PMID 38803919, 2024). "MMP-7 is also related to the severity of COVID-19 in obese diabetics." (PMID 37372128, 2023). "Indeed, epithelial cells from bronchoalveolar lavage fluid (BALF) on severe COVID-19 showed elevated frequencies of MMP-7+ and MMP-9+ and a tendency to increase portions of MMP-2+ and MMP-13+ compared to mild cases." (PMID 35625532, 2022).